JAK2 (Janus kinase 2)
Diseases named in the same sentence as JAK2 in open-access papers (continued):
Sharing a sentence is not in itself a finding about the gene and the disease.
myelofibrosis (continued). "Some studies have shown that the burden of JAK2 V617F alleles can correlate with the phenotypic presentation of MPN, severity of the disease phenotype, risk of thrombotic events, progression to post-PV myelofibrosis, and survival." (PMID 37370982, 2023). "In addition, when comparing the grade of myelofibrosis between these two groups, there was a slight increase in the frequency of patients with some form of fibrosis in the high positive JAK2 group and the difference was statistically significant (p = 0.023)." (PMID 37370982, 2023). "In JAK2 V617F murine models of MPN, EZH2 mutations induce a myelofibrosis-like phenotype." (PMID 37519812, 2023). "While the JAK2 inhibitor ruxolitinib provides some clinical benefit, there remains a substantial unmet need for novel targeted therapies to better modify the disease process or eradicate the cells at the heart of myelofibrosis pathology." (PMID 37253035, 2023). "The mutations described in the following sub-sections commonly co-exist with JAK2, MPL, and CALR mutations in patients with myelofibrosis and, while they fall within broad categories (such as proteins affecting splicing and epigenetic regulation), each has its own unique mechanism." (PMID 37760623, 2023). "It is hypothesized that the loss of NF1 could be a late event likely to give additional growth potential even to cells homozygous for JAK2-V617F and might contribute to disease progression towards secondary myelofibrosis." (PMID 35456443, 2022). "These preclinical studies and ongoing clinical trial data suggest impeding the anti-apoptotic nature of BCL-XL, and perhaps other BCL-2 family members, may improve JAK2 inhibitor therapy for myelofibrosis, and perhaps other MPN, patients." (PMID 35082276, 2022). "It is also the first reported case of JAK2 p.L611S in an adult with myelofibrosis." (PMID 35237453, 2022). "Furthermore, a characteristic clinical symptom of the iMCD-TAFRO syndrome is bone marrow fibrosis; the mechanism of myelofibrosis is believed to be the self-proliferation of cytokine-independent hematopoietic cells by JAK 2 activation." (PMID 36482523, 2022). "Ruxolitinib is one of the specific JAK1/JAK2 inhibitors approved by the FDA against myelofibrosis." (PMID 35401182, 2022). "Although JAK2 p.L611S mutation has not been reported with myelofibrosis or essential thrombocytosis, it has been reported in a child with congenital thrombocytosis." (PMID 35237453, 2022). "Treatment of myelofibrosis mononuclear cells with AVID-200 increased numbers of progenitor cells with wild type JAK2 but not mutated JAK2V617F284." (PMID 35773269, 2022). "JAK2-V617F is present in 95% of PV patients and 50–60% of ET and myelofibrosis patients." (PMID 35082276, 2022). "This dovetails nicely with ongoing work suggesting DUSP6 contributes to JAK2 inhibitor resistance and may be a therapeutic target in myelofibrosis, an unexpected finding given DUSP6 inhibition would in theory enhance ERK activity." (PMID 35082276, 2022). "In addition, the JAK1/JAK2 inhibitor, ruxolitinib, has also been approved for the treatment of myelofibrosis and polycythemia vera." (PMID 35631587, 2022). "Combined JAK1/2 and SMAD3 treatment proved to be the most efficient in preventing the myelofibrosis induced by BM-MSCs via neoplastic MPN mononuclear cells regardless of the presence of JAK2 mutation." (PMID 35288649, 2022). "Presence of a mutation in JAK2, CALR, and MPL is among the major criteria for the diagnosis of myelofibrosis (MF) or essential thrombocythemia (ET), while presence of JAK2 V617 or exon 12 mutations is among the major criteria for the diagnosis of polycythemia vera (PV)." (PMID 33909614, 2021). "Diagnosis of PMF requires demonstration of myeloproliferative mutational markers such as JAK2 or CALR mutation and evaluation of potential causes of secondary myelofibrosis, including infection, autoimmune diseases, chronic inflammatory disorders, malignancies, and toxic agents." (PMID 34749829, 2021).
myelofibrosis (continued). "Furthermore, JAK2-activating mutation has been observed in chronic myeloproliferative neoplasms (MPNs), such as chronic myeloid leukemia (CML), polycythemia vera and myelofibrosis." (PMID 34831142, 2021). "The discovery of JAK2V617F (valine 617 to phenylalanine) mutation in myelofibrosis uncovers the activated JAK–STAT (signal transducer and activator of transcription) signaling as a primary driver for myelofibrosis, and supports the rationale for treating myelofibrosis by JAK2 inhibition." (PMID 32947833, 2020). "Data regarding the impact of mutation order on clinical phenotype in myelofibrosis are still lacking, though we know that in patients with multiple mutations, JAK2 V617F was generally an earlier event in those with PMF." (PMID 33255170, 2020). "Fedratinib (INREBIC®, also known as SAR302503 or TG101348) is an oral, small molecule, selective Janus kinase 2 (JAK2) inhibitor, with activity against both wild-type and mutant JAK2, approved in the United States for the treatment of adult patients with myelofibrosis (MF)." (PMID 32886148, 2020). "Moreover, 4 therapeutic JAK2 inhibitors (ruxolitinib, fedratinib, momelotinib, and pacritinib) have either been approved or are in advanced clinical development for myelofibrosis." (PMID 31560729, 2019). "The vast majority of patients with myelofibrosis but without AML were found to be positive in their JAK2 V617F mutation status (81%)." (PMID 31555600, 2019). "Although myelofibrosis is characterized by mutations of JAK2 and calreticulin (CALR), these mutations are not useful to monitor response to therapy." (PMID 27167495, 2016). "Quantitative JAK2 mutation testing can not only provide prognostic information about MPN and monitor minimal residual disease after stem cell transplant for JAK2-positive patients with myelofibrosis but also be used to monitor disease progression and response to therapy." (PMID 27752371, 2016). "Depending on the beneficial effects of JAK2 inhibitors on inflammatory conditions observed in myelofibrosis, one may reasonably wonder whether other anti-inflammatory therapeutics could be useful." (PMID 26549943, 2015). "We recently showed that the JAK inhibitor ruxolitinib, which also has relative selectivity for JAK1 and JAK2 and is currently approved for myelofibrosis, reversed disease in three AA patients in an open-label clinical trial of oral drug in moderate-to-severe disease." (PMID 26137574, 2015). "Compared with JAK2 mutations, JAK2 fusions are probably associated with more aggressive diseases such as acute leukemias (myeloid or lymphoblastic), atypical CML (aCML), and myelofibrosis." (PMID 25789185, 2015). "This exploratory analysis indicates that improvement or even resolution of BMF may be achievable with JAK2 inhibitor therapy in some patients with MPNs and myelofibrosis." (PMID 26357842, 2015). "CALR mutations have been recently identified in a significant proportion of patients with thrombocythemia and myelofibrosis without JAK2 and MPL mutations." (PMID 25068507, 2014). "Among JAK2 inhibitors, ruxolitinib is the most advanced in development and has been approved by American and European drug regulatory agencies for the treatment of patients with myelofibrosis based on the results of two phase III trials 23,24." (PMID 24237791, 2013). "Our patient had been enrolled in the COMFORT-II study, a randomized, open-label Phase III study of oral JAK2 inhibitor Ruxolitinib versus best available therapy in patients with primary myelofibrosis, post-polycythemia vera myelofibrosis, and post-essential thrombocythemia myelofibrosis." (PMID 23039051, 2012). "Therefore, the activation of JAK2 and the increased levels of circulating proinflammatory cytokines seem to play an important role in the pathogenesis of myelofibrosis." (PMID 23039051, 2012).
myelofibrosis (continued). "Discovery of JAK2V617F mutation and current progress in the molecule targeted treatment technologies lead to the development of JAK2 inhibitors which seem toyield promising results in selected groups of patients with myelofibrosis and created a certain enthusiasm." (PMID 24744667, 2012). "The patient had the acquired point mutation V617F in the JAK2 gene but not the bcr-abl rearrangement and was treated for myelofibrosis with subsequent improvement of all haematological parameters without evidence of myelomatic evolution." (PMID 22084697, 2011). "In addition, JAK2 exon 12 mutation in PV2, and a thrombopoietin receptor MPLW515L/K mutation in ET and myelofibrosis are novel mutations that have been described in JAK2V617F mutation negative patients." (PMID 19232081, 2009). "Our findings suggest that some or all CIMF patients with JAK2 V617F might actually represent PV patients that progressed to myelofibrosis prior to diagnosis." (PMID 17183644, 2006). "However, we provide proof-of-principle that a JAK2 inhibitor should have therapeutic effects on the polycythemia, and perhaps myelofibrosis and hemostatic abnormalities, suffered by MPD patients carrying the JAK2 V617F mutation." (PMID 17183644, 2006). "This prolonged time may certainly reflect a more indolent nature of CALR-mutated myelofibrosis, or perhaps an initial reluctance to use ruxolitinib in JAK2-negative patients." (PMID 39831987, 2025). "We also investigated whether ruxolitinib has an impact on myelofibrosis in JAK2-V617F mice." (PMID 40413183, 2025). "It has been confirmed that mutations in three key genes, Janus kinase 2 (JAK2), calreticulin (CALR), and myeloproliferative leukemia oncogene (MPL), can increase the activity of blood-producing cells, make them grow more actively, and are associated with the development of myelofibrosis." (PMID 38339265, 2024). "Furthermore, we found that especially Momelotinib its important role as a JAK1/JAK2/ACVR1 inhibitor in alleviating myelofibrosis and anti‐inflammation, which may serve as a potential drug for COPD treatment." (PMID 38578019, 2024). "Importantly, it has also been established that myelofibrosis affecting JAK2 mutation-positive PV or ET does not have the same prognosis as classical JAK2 mutation-positive PMF." (PMID 39598101, 2024). "Up to 90% of patients with myelofibrosis harbor somatic mutations in the driver genes JAK2, CALR, or MPL, resulting in constitutive activation of the Janus kinase (JAK)‐signal transducer and activator of transcription (STAT) signaling pathway, most commonly gain‐of‐function JAK2 V617F mutation." (PMID 38406514, 2024). "The hypothesis has already been validated in a JAK2-mutated murine model, in which the expression of S100A8/A9 heterocomplex provoked inflammation and promoted myelofibrosis, both of which could be reversible upon treatment with a small molecule targeting S100A8/A9 signaling inhibition." (PMID 37240094, 2023). "Interestingly, fedratinib, a selective oral JAK2 inhibitor recently approved in the United States for treatment of adult patients with myelofibrosis, which has off-target activity against the VIPs BRD4, TBK1, MARK1 and CSNK2A2, also displayed a similar proviral effect in our disease system." (PMID 36305426, 2022). "Polycythemia vera, essential thrombocythemia and myelofibrosis share three common driver mutations: JAK2 V617F, CAL-R, and MPL are present in both myelofibrosis and essential thrombocythemia, while polycythemia vera harbors JAK2 V617F or mutations in the exon 12 of JAK2." (PMID 34441019, 2021). "Lack of clinical efficacy of Bortezomib in myelofibrosis may be linked to the need for blocking oncogenic driver mutations including Janus Kinase 2 and Calreticulin." (PMID 32331228, 2020).
myelofibrosis (continued). "Fedratinib, an oral, potent JAK2 inhibitor effective against wild-type and mutationally activated JAK2 and fms-like tyrosine kinase 3 (FLT3), was approved in 2019 for treatment of adult patients with intermediate-2 or high-risk primary or secondary myelofibrosis." (PMID 33322351, 2020). "Ruxolitinib is a potent JAK1 and JAK2 inhibitor that has demonstrated rapid and durable reductions in splenomegaly and improved symptoms and quality of life measures in the two phase 3 Controlled Myelofibrosis Study with Oral JAK Inhibitor Treatment (COMFORT) trials." (PMID 26380150, 2015). "Several explanations may account for the relatively disappointing results, including the genetic complexity of myelofibrosis, suppression of residual normal hematopoiesis as a result of JAK2 inhibition and the relatively low potency of available JAK2 inhibitors." (PMID 25316524, 2014). "JAK2 Inhibitors (Ruxolitinib and others) – JAK inhibitors in myelofibrosis and polycythemia vera have potent immunosuppressive effects." (PMID 41568391, 2025). "The subtle morphologic diagnosis and differentiation between coexisting JAK2 V617Fpos MPN and BCR::ABL1pos CML is complicated by the fact that left-shifted leukocytosis, thrombocytosis, BM hypercellularity and myelofibrosis can variably occur in both entities." (PMID 40681596, 2025). "Since its FDA approval in 2011 for the treatment of myelofibrosis, the clinical use of ruxolitinib as a selective JAK1 and JAK2 inhibitor has greatly expanded." (PMID 40117367, 2025). "Ruxolitinib as JAK1 and selectivity of JAK2 inhibitors, has been the United States Food and Drug Administration (FDA) approved for the treatment of b myelofibrosis." (PMID 40271123, 2025). "As previously noted, JAK2/CALR/MPL/TN mutational status did not appear to impact overall or leukemia-free survival in our current ET patient cohort while MPL mutation was associated with a significantly higher rate of progression to myelofibrosis, as per previous reports." (PMID 38238303, 2024). "CYT387, a drug for the treatment of myelofibrosis, can inhibit interferon and interferon-stimulated gene expression through JAK1/JAK2 (kinases mediating IFN signaling) and TBK1/IKKε (kinases mediating RLR and TLR signaling) pathways." (PMID 39738014, 2024). "The mechanism of action of JAK2 inhibitors in treating ILD requires further discussion, and a clear understanding is needed as to why patients with myelofibrosis develop ILD." (PMID 39659792, 2024). "Momelotinib, an inhibitor of JAK1, JAK2, and ACVR1, was approved in 2023 for the treatment of patients with myelofibrosis and anemia and has shown spleen and symptom benefits in phase 3 trials in this patient population." (PMID 38406514, 2024). "For instance, selective JAK1 and JAK2 Ruxolitinib has been shown to reduce VTE events in patients with polycythaemia vera and myelofibrosis." (PMID 36615007, 2022). "In mice models, the MPN phenotype induced by JAK2 V617F was accentuated in JAK2 V617F/EZH2 (wild type/wild type) mice, resulting in very high platelet and neutrophil counts, more advanced myelofibrosis, and reduced survival." (PMID 35562964, 2022). "Ruxolitinib (Novartis) is another approved inhibitor for the treatment of myelofibrosis, which targets both JAK1 and JAK2 and is currently being used in a number of clinical studies (phase I, II, and III) in solid tumors including BC." (PMID 35401182, 2022). "Pacritinib, a JAK2/FLT3 inhibitor, was approved by the FDA for the treatment of myelofibrosis in adult patients with thrombocytopenia." (PMID 35631587, 2022). "Baricitinib and Fedratinib, which show selectivity for JAK2 over JAK3, have gained approval for myelofibrosis while Upadacitinib, which has selectivity for JAK1, has obtained approval for the treatment of rheumatoid arthritis." (PMID 33980892, 2021). "Pacritinib is a JAK2/FLT3 inhibitor with IRAK1 inhibiting capabilities, presently under clinical investigation for myelofibrosis and glioblastoma." (PMID 34355696, 2021).
myelofibrosis (continued). "Examples of repurposed drugs are ruxolitinib and momelotinib, which are approved for myelofibrosis, targeting the JAK1/JAK2 gene pathway." (PMID 34721386, 2021). "Moreover, myelofibrosis was a very common phenomenon in the bone marrow biopsy of this atypical MPN, that is, 11 of these 13 cases showing grade 2 to 3 reticulin fibrosis, which is consistent with another case series of concurrent BCR-ABL1 fusion and JAK2 V617F mutation." (PMID 32000382, 2020). "Ruxolitinib is a JAK1/JAK2 inhibitor approved by the Food and Drug Administration (FDA) for psoriasis, myelofibrosis, and rheumatoid arthritis." (PMID 32527304, 2020). "Upadacitinib (anti-JAK1), fedratinib (anti-JAK2), and oclacitinib (anti-JAK1) were approved by FDA for rheumatoid arthritis, myelofibrosis, and dermatitis, respectively." (PMID 32527304, 2020). "We validate an economic model for PV that uses Janus Kinase 2 (JAK2) burden as a surrogate endpoint to predict DP (thrombosis, myelofibrosis, and acute leukemia) and overall survival (OS) based on progression-specific mortality." (PMID 32685599, 2020). "In this study, we show that specific inhibition of HSP27 using OGX-427 limits myelofibrosis progression in two murine models of MF15, 22, 23 and affects the JAK2/STAT signalling pathway." (PMID 29650953, 2018). "Preventing and reducing STAT5 activation through the use of JAK2 inhibitors proved clinical efficacy in patients with myelofibrosis and PV, and the first-in-class JAK1 and JAK2 inhibitor ruxolitinib was approved recently for selected categories of patients." (PMID 29228564, 2017). "Ruxolitinib is a Janus kinase (JAK) (JAK1/JAK2) inhibitor that has demonstrated superiority over placebo and best available therapy (BAT) in the Controlled Myelofibrosis Study with Oral JAK Inhibitor Treatment (COMFORT) studies." (PMID 27211272, 2016). "The results of this exploratory analysis support this hypothesis by demonstrating that prolonged treatment with the JAK2 inhibitor, fedratinib, was associated with stabilisation or improvement of BMF in a proportion of patients with PMF, post-ET myelofibrosis and post-PV myelofibrosis." (PMID 26357842, 2015). "More recently, it was also observed that the effect of JAK inhibitors and especially the dual JAK1/JAK2 inhibitor INCB18424 (ruxolitinib, JAKAVI) was enhanced by PU-H71 in a murine model of myelofibrosis." (PMID 26549943, 2015). "The results are quite expected since AZD1480 is known to be a potent, selective JAK2 inhibitor, while ruxolitinib is a potent JAK1 and JAK2 inhibitor approved by FDA for treatment of myelofibrosis." (PMID 25036984, 2014). "This was attributed to the extensive marrow fibrosis, raising the possibility of myelofibrosis, which prompted our MPN investigation and JAK2 testing." (PMID 24744787, 2014). "A number of compounds have entered clinical trials and INCB018424, a Jak1 and Jak2 targeting compound, was recently approved by the FDA and the European Commission for treatment of myelofibrosis." (PMID 23301855, 2013). "Clinical trials using Jak2 inhibitors including INCB018424, CYT387 and SAR302503 (TG101380) have been completed or are underway to treat primary myelofibrosis." (PMID 24086539, 2013). "Ruxolitinib, an oral JAK1 and JAK2 inhibitor, is the first JAK inhibitor that has been approved by the FDA for the treatment of myelofibrosis." (PMID 24199193, 2013). "In 2012, one JAK2/JAK1 inhibitor, ruxolitinib, was approved by FDA for the treatment of myelofibrosis, following two phase III clinical trials 14–15." (PMID 24251790, 2013). "Numerous clinical trials with JAK2 inhibitors are being conducted in MPN patients, particularly with myelofibrosis 19,20." (PMID 24237791, 2013). "As fedratinib, a selective JAK2 inhibitor is approved for use in myelofibrosis (but not for PV as in our case), the patient was switched to fedratinib without experiencing a relapse of histoplasmosis or other fungal infections." (PMID 41164159, 2025).